IGF1 (insulin like growth factor 1)
Diseases named in the same sentence as IGF1 in open-access papers (continued):
Sharing a sentence is not in itself a finding about the gene and the disease.
diabetes (continued). "There was a higher prevalence of shoe size increase: (43% vs 11%; p = 0.027) paresthesia (71% vs 28%; p = 0.023), hoarse voice (57 vs 18%; p = 0.021) arthralgia (100% vs 47%; p = 0.005) and diabetes (71% vs 15%; p = 0.001) in patients with persistently elevated IGF-1." (PMID 28898247, 2017). "Increased IGF-1 mRNA levels in the liver may compensate to overcome the hyperglycemic state during the early stage of diabetes." (PMID 27070590, 2016). "In addition, T2D is the result of a complex interaction of environmental and genetic factors, being difficult to establish the role of each one in the pathogenesis of diabetes and in the levels of IGF-1." (PMID 26733412, 2016). "Indeed IGF-1 mRNA has been found to be reduced in the eye in early stages of clinical and experimental diabetes, while IGF replacement therapy counteracts proapoptotic abnormalities preceding retinal cell degeneration in diabetic rats." (PMID 27123463, 2016). "The therapy with octreotide in subjects with acromegaly improves the glucose profile if normal glycaemia is found at baseline according to GH and IGF1 lowering and, if the patients already have diabetes mellitus, only partial glucose control is found, as GH and IGF1 are inadequately suppressed." (PMID 26361517, 2015). "Similarly, Igfbp1, an important regulator of insulin like growth factor 1 (IGF1) activity, showed an almost five-fold increase in SO-HFD versus HFD livers: increased hepatic expression of Igfbp1 is associated with diabetes." (PMID 26200659, 2015). "Also, alterations in the IGF-1 gene leads to lower levels of IGF-1, in turn linked to a higher risk of developing both diabetes and myocardial infarction." (PMID 26577692, 2015). "These cardiac changes are due mainly to the GH and IGF1 excess, but the systemic arterial hypertension, glucose intolerance or diabetes, obesity and dyslipidemia frequently present in these patients are also likely to contribute to cardiovascular complications." (PMID 26429918, 2015). "The relative or absolute insulin deficiency of diabetes may have rendered her less sensitive to the insulin-enhanced hepatic production of IGF-1 and may explain why her IGF-1 levels increased with insulin and metformin treatment." (PMID 26514337, 2015). "IGF-1 is also strongly linked to glucose-insulin pathways, however, the link to diabetes is not altogether easy, as both high and low levels of IGF-1 have been shown to correlate with subsequent onset of diabetes." (PMID 26577692, 2015). "Although GH/IGF-1 excess provides a probable pathophysiological explanation, the degree of IGF-1 excess and the role in acromegaly-associated neoplasms of diabetes, a common comorbidity in acromegaly with known association with cancer, remains unclear." (PMID 25996963, 2015). "Similar changes in IGF1R signaling have been described in diabetes, suggesting that decreased IGF1/IGF1R signaling might be involved in the pathogenesis of both diabetes and AD." (PMID 25268761, 2014). "However, the mean IGF1 bioactivity became >+2 s.d. suggesting that diabetes can reduce IGF1 bioactivity in acromegalic subjects." (PMID 24692508, 2014). "Furthermore, the effect of curcumin on gene expression of Bcl-2 and IGF-1 in streptozotocin-induced diabetes in rats was also determined." (PMID 24364912, 2013). "When we statistically analyzed the IGF-1 alterations according to age, duration of diabetes mellitus, Wagner classification, initial and final HbA1C values, and HbA1C alterations, we could not find a significant difference." (PMID 23671876, 2013). "Therefore, the aim of the present study was to investigate the association between intra-prostatic levels of IGF-1, IGF-2 as well as to evaluate the role of locally expressed IGFBP-3 in BPH development in pre-diabetes." (PMID 24367483, 2013).
diabetes (continued). "Structural studies elucidate how each of the three ligands, insulin, IGF-1, and IGF-2, interacts differently with isoforms A and B of the insulin receptor and with type I IGF receptor and explain how these protagonists contribute to diabetes-associated cancer." (PMID 23983688, 2013). "Even for diabetes, insulin, which has been the main glucose lowering treatment, has been evaluated in combination with recombinant human insulin-like growth factor I (IGF1), a pathway that if restored can lead to much higher glucose lowering than insulin alone." (PMID 23210531, 2012). "Thus, among the five analogues used for the treatment of diabetes, only glargine showed a profile similar to that of IGF1 towards hybrid receptors." (PMID 22848683, 2012). "In our study, the effect of STZ-induced diabetes has been observed as a decrease in IGF-1 levels." (PMID 22194889, 2011). "The increased IGF-1 level in the pancreas led us to hypothesize that PR-ASG is protective for islet β-cells against the extensive injury of advanced or severe diabetes." (PMID 22194889, 2011). "This increased risk is hypothesized to be secondary to several factors, such as increased circulating insulin and insulin-like growth factor (IGF-1), and to effects of treatment for diabetes." (PMID 21672406, 2011). "Perhaps in conditions of systemic insulin/insulin growth factor 1 (IGF-1) signaling reduction the metabolic syndromes (such as diabetes) that stem from the liver hide the potential health benefits of reduced insulin/IGF-1 signaling in other tissues, such as the brain." (PMID 27713238, 2009). "The chronic elevation of GH and the resulting high circulating levels of insulin-like growth factor-1 (IGF-1) cause the characteristic tissue overgrowth and a number of associated comorbidities, including several metabolic changes, such as glucose intolerance and overt diabetes mellitus (DM)." (PMID 39859181, 2025). "Evidence indicates that the WFS1 gene plays a pivotal role in modulating the insulin-like growth factor-1 (IGF-1) and growth hormone (GH) signaling pathway, with genetic perturbations predisposing to impaired somatic growth and metabolic disturbances, including diabetes mellitus." (PMID 40538800, 2025). "Consequently, IGF-1 may serve as an integrative biomarker of metabolic health in elderly diabetics, reflecting the collective status of insulin signalling, inflammation, and metabolic dysregulation." (PMID 41393761, 2025). "Therefore, activating IGF1 emerges as a potential target for diabetes management." (PMID 40657379, 2025). "By implementing strict inclusion/exclusion criteria to account for potential confounders such as diabetes, infection, and hypothyroidism, our findings suggest a potential independent negative association between serum IGF-1 levels and hypsarrhythmia that warrants further investigation." (PMID 40371354, 2025). "Therefore, current research aims to identify the influence of diabetes on lipid profile, serum PSA, and endocrine factors such as insulin, IGF-1, and testosterone in prostate cancer and its association with progression, risk, and aggressiveness of prostate cancer." (PMID 41367482, 2025). "Therefore, the increased IGF-1 and visfatin after schistosome infection may be important for the treatment of diabetes." (PMID 39590301, 2024). "Also, in type 2 diabetes mellitus, the levels of IGF-1, IGFBP-3 and IGFBP-1 may be extremely variable." (PMID 39444449, 2024). "Moreover, it is important to note that reduced insulin and/or IGF-1 signalling noted in other contexts, such as type 2 diabetes mellitus, are highly distinct from inherited reduction in insulin and/or IGF-1 receptor expression, making these difficult to compare." (PMID 39247377, 2024). "Moreover, the diabetes-related histological and functional changes, especially fibro-genesis, could be attenuated by IGF-1/IGF-1R inhibitors." (PMID 38375323, 2024).
diabetes (continued). "In contrast, the GRS for lower FEV1/FVC specific to PI3K–Akt signaling was associated with increased asthma risk, lower IGF-1, lower liver enzymes (ALT, AST and gamma glutamyltransferase (GGT)), lower lymphocyte counts, raised eosinophils, lower fat mass and BMI, and reduced diabetes risk." (PMID 36914875, 2023). "Moreover, skin IGF-1 could also contribute to the increased levels of plasma IGF-1 present in type 2 diabetes mellitus." (PMID 36722656, 2023). "The alterations observed in the expression of Tnf-α, F4/80, Il-6, Tgf-β1, Igf-1, and BDNF could predispose to the disruption of uninjured skin homeostasis, suggesting that these alterations are the primary cause of impaired wound healing in diabetes." (PMID 36722656, 2023). "It is not known whether low IGF-1 levels are also associated with an increased incidence of chronic diseases in adulthood, such as diabetes, hypertension, and coronary heart disease, in chronically malnourished children." (PMID 37111069, 2023). "Studies in CRC patients with diabetes mellitus (DM) (n = 125) showed a positive correlation between IGF-1, IGF-1R and IR expressions in all cancer tissues." (PMID 36835075, 2023). "The improvement in glycaemic status and IGF-1 level in diabetic rats treated with TDF-AgNPs may be due to antidiabetic and antioxidant effects of silver nanoparticles in the conjugates via scavenging the free radicals caused by TDF and diabetes." (PMID 35122679, 2022). "Furthermore, we found that i.t. administration of rIGF-1 as well as i.t. or i.p. treatment with EGCG alleviated the diabetes-induced pain-like behaviors, reduced neuroinflammation, averted the M1 microglia polarization, and recovered the microglial IGF-1 expression." (PMID 35401920, 2022). "In addition, in the subjects without diabetes, fasting hyperglycemia was found to be significantly linked to low IGF-1 levels, suggesting that low IGF-1 levels are associated with the pre-diabetic condition in obese population." (PMID 36418379, 2022). "Although IGF1, IGFBP3, and IGFALS may be associated with diabetes, the levels of these proteins in our study in severe patients without diabetes were also very low, indicating that their decline was not only due to diabetes." (PMID 35958562, 2022). "In particular, diabetes may be a major confounding factor for circulating IGF-1 levels." (PMID 36120463, 2022). "Moreover reduced IGF-1 levels may be observed children with malnutrition, hypothyroidism, hepatic disease or diabetes mellitus and there is overlap between normal and GHD children." (PMID 35250894, 2022). "In addition, dietary diary consumption (as measured by IGF-1) was found to increase probability for cancer by about 48%, while plant-based nutrition reduced diabetes by about 27% and meat consumption increased probability for diabetes by about 50% on average." (PMID 37928317, 2021). "Moreover, high endogenous insulin concentrations observed in patients with type 2 diabetes mellitus are associated with reduced hepatic synthesis of IGFBP-1 (the main IGF-1 binding globulin), leading to increased bio-availability of IGF-1 and possible enhancement of its known mitogenic effects." (PMID 34680546, 2021). "However, this article showed that growth factors, including vascular endothelial growth factor (VEGF), IGF-1, and tumor necrosis growth factor, may have a protective role in the progression and development of diabetes complications." (PMID 33905470, 2020). "In general, systemic administration of recombinant human IGF-1 may reduce the levels of insulin and glucose in diabetes patients with reduced response to insulin, which indicates that IGF-1 is capable of increasing insulin sensitivity and has broad effects on IR and hyperglycemia." (PMID 33905470, 2020).
diabetes (continued). "Another study showed that spirulina could prevent the negative effects associated with reduced circulating IGF-1 levels and high hepatic fat content in a protein deficiency model as well as animal models of diabetes and non-alcoholic steatohepatitis." (PMID 32344533, 2020). "However, some conditions may determine low IGF-1 levels as chronic diseases as uremia, hepatic failure and uncontrolled diabetes mellitus, poor nutritional status and advanced age." (PMID 31939489, 2019). "In addition to hyperglycemia in diabetes, hyperinsulinmia and an increase in bioavailable insulin like growth factor 1 (IGF-1) may play an important role in neoplastic transformation." (PMID 30541490, 2018). "However, the literature on maternal IGF-1 in pre-existing diabetes is conflicting." (PMID 30108547, 2018). "Thus, IGF-1 can be used to treat diabetes, and it can also affect AD." (PMID 29180962, 2017). "IGF-1 signaling pathway might be the connecting bridge for diabetes and AD therapy." (PMID 29180962, 2017). "The presence of excess GH and IGF-1 leads to a series of metabolic symptoms, including glucose intolerance (GI), diabetes mellitus (DM), hypertension, and several other endocrine disorders." (PMID 28380462, 2017). "Interestingly, in addition to its IGF-1-lowering effect, pegvisomant may also improve glucose homeostasis in patients with diabetes mellitus." (PMID 27039081, 2016). "For example, serum IGF-1 levels have been shown to be negatively correlated with age and BMI in healthy adults and are modulated by medical conditions, which occur frequently in the elderly, for example, diabetes mellitus, depression/anti-depressant medication or thyroid dysfunction." (PMID 26967642, 2016). "In another study among patients with impaired glucose tolerance and subjects with and without diabetes, low plasma IGF-1 concentrations were significantly associated with the presence of metabolic syndrome and were inversely associated with a number of individual metabolic syndrome components." (PMID 27343122, 2016). "Diabetes-induced aberrant overexpression of miR-320 in cardiac myocytes and further delivery of this miRNA to myocardial ECs by cardiac exosomes results in downregulation of the endothelial production of Hsp20, insulin-like growth factor-1 (IGF-1) and transcription factor Ets2." (PMID 26742038, 2016). "In this setting, the low serum IGF-1 level could be attributed to poorly controlled diabetes." (PMID 26514337, 2015). "In 20 patients who were free of diabetes before pegvisomant introduction, the mean fasting blood glucose level did not change on pegvisomant: their values were 5.4±1.4, 5.1±0.9 and 5.6±1.8 mmol/l, respectively, before pegvisomant, at IGF1 normalization, and at the last available determination (NS)." (PMID 26429918, 2015). "However, whether the overexpression of the klotho gene inhibits diabetes-induced renal hypertrophy through inhibition of the IGF-1 signaling pathway remains to be elucidated." (PMID 25695625, 2015). "Numerous studies in mammals have reported that IGF-1 concentrations decline with advancing age, showing the association of IGF-1 with longevity and age-related diseases (e.g., cancer, cardiovascular disease, diabetes, osteoporosis, and neurodegenerative diseases)." (PMID 25734326, 2015). "Therefore, chronic alterations of insulin/IGF1 levels (or biological activity) because of systemic metabolic dysfunction like in obesity or diabetes are likely to create an environment in which cancer cells that depend on these factors thrive particularly well." (PMID 26284118, 2015). "Previous research showed that cancer patients with diabetes may have increased tumor cell proliferation and metastatic capacity as a consequence of the high insulin or increased free insulin-like growth factor (IGF-1) levels in hyperinsulinemic states." (PMID 25350747, 2014).
diabetes (continued). "Hence, impaired insulin and IGF-1 signaling resulting in decreased GSK-3β (Ser 9) expression allows for phosphorylation of p-GSK-3β, a potent phosphorylating stress kinase, which has also been implicated in Alzheimer-like changes in diabetes." (PMID 19834568, 2009). "This may be related to the decreased levels in diabetes of insulin and IGF1, which are both powerful activators of the mTOR pathway and which could act on the insulin-like growth factor receptor which is expressed on small and medium sized dorsal root ganglia neurons." (PMID 18398477, 2008). "The expressions of IL17A, ACE, TLR4, and IL6 are up-regulated with diabetes that promote the progression of gangrene, whereas the expressions of FGF2 and IGF1 are down-regulated." (PMID 40657379, 2025). "Determinants of the “low leptin/IGF-1/HbA1c” biomarker status included younger age, lower BMI, and prolonged breast-feeding duration; but particularly several parental characteristics revealed strong association such as no family history of diabetes and hypertension, and lower maternal BMI." (PMID 39899498, 2025). "In the context of diabetes, IGF-2 mRNA levels in the retina decreased, while IGF-1 or IR mRNA levels remained unaffected." (PMID 38300646, 2024). "For instance, the presence of type 2 diabetes mellitus (T2DM) and IGF-1 levels > 1.5 × ULN motivate to PEGV shift after SRLs resistance (86% each), and the recurrence of previously controlled headaches is a concern for 83% of the panelists." (PMID 38809458, 2024). "Other recent data show that IGF1 and IGF1R expression correlated with AGEs in colorectal cancer patients who also had type 2 diabetes mellitus 111]." (PMID 38892104, 2024). "Age > 70 years, smoking history, diabetes history, prolonged use of perioperative antibiotics, and elevated CRP, IL-6, and IGF-1 levels on the 1st day after surgery have an impact on postoperative lung infection in elderly LC patients." (PMID 39495987, 2024). "Age > 70 years, smoking history, diabetes history, prolonged use of perioperative antibiotics, and elevated CRP, IL-6, and IGF-1 levels on the 1st day after surgery have an impact on postoperative lung infection in elderly patients with LC." (PMID 39495987, 2024). "We conducted a comparative analysis of baseline marker levels between the study and control groups, including adiponectin, leptin, IL6, TNFα, IGF1, and IGF2, while also adjusting for BMI, parity, and diabetes." (PMID 38339282, 2024). "The (3S)-vestitol effect in reducing the expression of Scd1, Scd2, Egr1 and its impact on increasing the Apoe, Igf1, and Fgf10 expression demonstrates the positive effects that this molecule, derived from Brazilian red propolis, may have on metabolic diseases such as atherosclerosis and diabetes." (PMID 35631379, 2022). "Most patients with diabetes have hyperinsulinemia, IGFBP is suppressed to a certain extent, and the level of free IGF-1 is relatively high." (PMID 36329881, 2022). "On the contrary, several studies have found a connection between low levels of IGF‐1 and conditions such as cardiovascular diseases (CVD), diabetes mellitus, osteoporosis, and sarcopenia." (PMID 35048526, 2022). "An example of fetal programming is the IGF-1 gene: from birth, high IGF-1 DNA methylation can be observed to screen infants with higher risks of developing cardiovascular disease or diabetes in adulthood." (PMID 35159377, 2022). "Serum IGF-1 levels were found to be negatively correlated with FRAX-MOF and FRAX-HF in patients with diabetes." (PMID 36010307, 2022). "Present knowledge shows that lifelong IGF1 deficiency in untreated patients with LS does not seem to markedly influence their lifespan, unless they neglect to treat in time the metabolic and cardiovascular complications of this condition, such as diabetes mellitus and hyperlipidemia." (PMID 34769292, 2021).